IRF2BP2 (interferon regulatory factor 2 binding protein 2)
Description:
Acts as a transcriptional corepressor in a IRF2-dependent manner; this repression is not mediated by histone deacetylase activities. Represses the NFAT1-dependent transactivation of NFAT-responsive promoters. Acts as a coactivator of VEGFA expression in cardiac and skeletal muscles. Plays a role in immature B-cell differentiation.
Synonyms: IRF-2BP2; LRIR2; CVID14
Tractability: PROTAC: UniProt records ubiquitination sites on it; ubiquitination databases record sites on it; its protein half-life has been measured.
Gene: Protein-coding gene on chromosome 1 (234,602,300 to 234,610,178, reverse strand). Ensembl gene ENSG00000168264.
Subcellular location: Cytoplasm; Nucleus
Subcellular location (Human Protein Atlas): Nucleoplasm
Gene Ontology:
Molecular function: transcription corepressor activity
Biological process: immature B cell differentiation; negative regulation of transcription by RNA polymerase II; regulation of transcription by RNA polymerase II
Cellular component: nucleoplasm; nucleus; cytoplasm
Genetic constraint (gnomAD): Loss-of-function variants: 8 observed, 20.36 expected, observed/expected ratio (o/e) 0.39, 90% interval 0.23 to 0.71. The synonymous counts are far from expectation, so gnomAD's model fits this gene poorly and the ratio says little. Missense variants: 974 observed, 665.17 expected, observed/expected ratio (o/e) 1.46, 90% interval 1.39 to 1.54. Synonymous variants: 555 observed, 327.52 expected, observed/expected ratio (o/e) 1.69, 90% interval 1.58 to 1.82.
Gene-disease validity (ClinGen):
ClinGen rates the evidence that IRF2BP2 causes each of these diseases.
immunodeficiency, common variable, 14 (autosomal dominant): Limited.
Homologues: Orthologues: chimpanzee IRF2BP2 (99% identical), macaque IRF2BP2 (99% identical), dog IRF2BP2 (95% identical), pig IRF2BP2 (95% identical), mouse Irf2bp2 (87% identical), rat Irf2bp2 (86% identical), tropical clawed frog irf2bp2 (64% identical), zebrafish irf2bp2b (54% identical), Drosophila melanogaster Pits (33% identical), zebrafish irf2bp2a (27% identical), Caenorhabditis elegans ifbp-1 (26% identical), Caenorhabditis elegans ztf-11 (7% identical). Paralogues in human: IRF2BPL (55% identical), IRF2BP1 (37% identical), MYT1 (20% identical), MYT1L (18% identical), ST18 (17% identical).
Diseases named in the same sentence as IRF2BP2 in open-access papers:
IRF2BP2 is named in the same sentence as 77 diseases in open-access papers, as found by Europe PMC text mining. Sharing a sentence is not in itself a finding about the gene and the disease. The quoted sentences say what the papers report.
atherosclerosis (6 papers, 2017 to 2024). A disease characterized by the build-up of fatty material and calcium deposition in the arterial wall resulting in partial or complete occlusion of the arterial lumen. "In a mouse atherosclerosis model, IRF2BP2-deficient macrophages exhibited pro-inflammatory traits that responded to KLF2 restoration with enhanced anti-inflammatory features." (PMID 39385609, 2024). "IRF2BP2 (interferon regulatory factor 2-binding protein 2) was found to attenuate macrophage-mediated inflammation and susceptibility to atherosclerosis." (PMID 35203463, 2022). "Our previous studies showed that IRF2 binding protein 2 (IRF2BP2) regulates peripheral macrophage polarization, limits their inflammatory response and reduces susceptibility to atherosclerosis." (PMID 28769762, 2017). "Our studies further demonstrated that ablation of IRF2BP2 in macrophages worsens atherosclerosis in mice, and a deletion variant that lowers IRF2BP2 expression predisposes to coronary artery disease in humans." (PMID 28769762, 2017). "Since loss of Irf2bp2 in mouse macrophages worsened atherosclerosis, we asked whether this deletion variant associated with coronary artery disease (CAD) in a subset of the OHGS consisting of 1,066 cases of CAD and 1,011 controls." (PMID 34760935, 2021). "Repressive actions of IRF2BP2 have been shown to attenuate atherosclerosis and CN inflammation, partly suppressing production of inflammatory cytokines." (PMID 35538558, 2022). "Selective ablation of Irf2bp2 in macrophages triggers an inflammatory response and worsens atherosclerosis in mice." (PMID 35865523, 2022). "Irf2bp2 is down regulated by lipopolysaccharides (LPS) and ablation of Irf2bp2 in macrophages activates inflammation, impairs macrophage cholesterol efflux and worsens atherosclerosis." (PMID 35865523, 2022). "Macrophages lacking Irf2bp2 worsened atherosclerosis in murine models due in part to impaired macrophage cholesterol export." (PMID 34760935, 2021). "Together with recent work tying ELAVL1 in mediating the pro-atherosclerosis effect of a macrophage-specific lncRNA, these studies point to an interesting parallel that may contribute to arterial calcification mediated through ELAVL1 modulation of IRF2BP2." (PMID 34760935, 2021).
breast carcinoma (6 papers, 2014 to 2024). "IRF2BP2 interacts with the proapoptotic NRIF3 to control Caspase-2-dependent cell death in breast cancer cells." (PMID 38409107, 2024). "IRF-2BP2 is a transcriptional repressor of the proapoptotic gene FASTKD2 (Fas-activated serine-threonine kinase domain 2) in breast cancer cells." (PMID 34356858, 2021). "Furthermore, IRF2BP2 also regulates a variety of cellular functions in breast cancer, leukemia, and chondrosarcoma." (PMID 38409107, 2024). "One possible mechanism for the higher constitutive expression of PD-L1 in certain basal breast cancer cell lines is higher levels of STAT1 and lower levels of IRF2BP2 expression." (PMID 24551119, 2014).
chondrosarcoma (4 papers, 2019 to 2025). A malignant cartilaginous matrix-producing mesenchymal neoplasm arising from the bone and soft tissue. "Furthermore, a newly discovered fusion of genes encoding IRF2BP2 and the transcription factor CDX1 was reported in mesenchymal chondrosarcomas." (PMID 33996817, 2021).
prostate carcinoma (4 papers, 2018 to 2024). A carcinoma that arises from epithelial cells of the prostate gland. "In this study, we systematically analyze the effects of SPOP mutants derived from prostate cancers and endometrial cancers on IRF2BP2 and find the differential outcomes." (PMID 38409107, 2024). "We find that five of these genes (IRF2BP2, EDARADD, GPI, HMOX1, KIF3C) were over-expressed in patient samples, and the overexpression was significantly associated with prostate cancer relapse (the onset of metastatic disease) as individual and as a group." (PMID 30478344, 2018). "Interestingly, we found that menin could modulate apoptosis via interacting with IRF-2BP2 (interferon regulatory factor-2 binding protein 2) that was identified as an apoptotic protein and its knockdown leads to apoptosis of breast and prostate cancer cells but not of other cell types." (PMID 34356858, 2021).
Stroke (4 papers, 2017 to 2025). Sudden impairment of blood flow to a part of the brain due to occlusion or rupture of an artery to the brain. "IRF2BP2 is necessary to mediate the anti-inflammatory and protective effects of IFN-β cytokines on stroke injury, and IRF2BP2-deficient microglia block the anxiolytic effect of enhanced postnatal care (EPC) by reducing inflammatory cytokine expression in the hypothalamus." (PMID 33996817, 2021). "Thus, we cannot exclude the contribution of infiltrating M1 (inflamed) IRF2BP2-deficient macrophages to worsen stroke outcomes." (PMID 28769762, 2017). "Thus, inflammation caused by ischemic brain injury would suppress IRF2BP2 expression and this may compromise the full beneficial effect of IFNβ to limit stroke injury." (PMID 28769762, 2017). "In summary, IRF2BP2 expression in macrophages/microglia is important to limit inflammation and stroke injury, in part by mediating the beneficial effect of IFNβ." (PMID 28769762, 2017). "Antagonism of miR-155 promotes stroke recovery, a process that likely involves increasing IRF2BP2 protein levels." (PMID 28769762, 2017). "Since IRF2BP2 modulates interferon signaling, and interferon beta (IFNβ) has been reported to be anti-inflammatory and reduce ischemic brain injury, we asked whether loss of IRF2BP2 in macrophages/microglia would affect the response to IFNβ in our stroke model." (PMID 28769762, 2017). "Thus, IRF2BP2 in microglia/macrophages is necessary to mediate the anti-inflammatory and protective effect of IFNβ on stroke injury." (PMID 28769762, 2017). "We also tested whether IFNβ would limit stroke injury and whether IRF2BP2 is required for the effect of IFNβ." (PMID 28769762, 2017). "Future studies will be required to test whether antagonism of miR-107 and miR-155 can maintain IRF2BP2 expression after stroke to improve the therapeutic effect of IFNβ for stroke recovery." (PMID 28769762, 2017).
viral infection (4 papers, 2023 to 2025). "A primate-specific lncRNA CHROMR can restrict viral infection of macrophages by sequestering the IFN regulatory factor (IRF)-2-dependent transcriptional corepressor IRF2BP2, thereby promoting the transcription of the ISG network." (PMID 37108410, 2023). "In this study, we report five novel loss-of-function (LoF) mutations in IRF2BP2 that likely cause primary immunodeficiency, with CVID as more frequent phenotype, variable expression of inflammatory gastrointestinal features, and one patient with predisposition of viral infection." (PMID 37876937, 2023). "LncRNA CHROMR can shape active ISG promoters by binding to IRF-2 binding protein 2 (IRF2BP2), and functions in limiting viral infection of macrophages." (PMID 39137200, 2024). "Expression of CHROMR is crucial for restricting viral infections in macrophages, and CHROMR can license IRF-dependent signaling and transcription of the ISGs network by sequestering the interferon regulatory factor (IRF)-2-dependent transcriptional corepressor IRF2BP2." (PMID 40285022, 2025).
acute promyelocytic leukemia (3 papers, 2021 to 2023). An aggressive form of acute myeloid leukemia (AML), characterized by arrest of leukocyte differentiation at the promyelocyte stage, due to a specific chromosomal translocation t(15;17) in myeloid cells. "In fact, the sequence of IRF2BP2 has an oncogenic role when it fuses with the RARA gene, previously reported in patients with promyelocytic leukemia." (PMID 37876937, 2023).
leukemia (3 papers, 2019 to 2025). A malignant (clonal) hematologic disorder, involving hematopoietic stem cells and characterized by the presence of primitive or atypical myeloid or lymphoid cells in the bone marrow and the blood. "Within this dataset, genes such as CBFB, SEPTIN9, CBFA2T3, CD1A, and ERG have been previously reported to be closely associated with leukemia development and progression. qPCR analysis further confirmed the reduced expression levels of these genes in IRF2BP2‐knockdown cells." (PMID 39454110, 2024). "Notably, IRF2BP2 was recently shown to interact and repress the function of the AP1 heterodimer ATF7/JDP2 in leukemia cells." (PMID 39752494, 2025).
antibody deficiency (2 papers, 2020 to 2023). "On the other hand, the expected phenotype of patients with LoF mutations in IRF2BP2 include as major features CVID, hypogammaglobulinemia and other observed features include enteropathy and autoimmune manifestations." (PMID 37876937, 2023).
Anxiety (2 papers, 2017 to 2022). Intense feelings of nervousness, tension, or panic often arise in response to interpersonal stresses. "Our study indicates that IRF2BP2-deficient microglia block the EPC-mediated suppression of anxiety and points to prostaglandin D2 involvement in this process." (PMID 28852125, 2017). "Ablation of Irf2bp2 in microglia hinders recovery from focal ischemic brain injury and blocks the anxiety-reducing effect of enhanced perinatal maternal care." (PMID 35865523, 2022).
colitis (2 papers, 2023 to 2024). Inflammation of the colon. "Furthermore, in mouse colons, NaOH that reduces protein levels of IRF2BP2, induces a myeloid-BiP-dependent colitis." (PMID 39737965, 2024). "It is very well established that the IRF2BP2 gene should be included in genetic testing for CVID, accordingly it should be suspected and recommend IRF2BP2-gene screening in cases with severe colitis with recurrent respiratory and gastrointestinal infections." (PMID 37876937, 2023).
common variable immunodeficiency (2 papers, 2022 to 2025). "It was shown that an AD GOF mutation of IRF2BP2 was implicated in a familial form of common variable immunodeficiency (CVID)." (PMID 35538558, 2022). "Recently, IRF2BP2 variants have emerged as rare monogenic causes of common variable immunodeficiency disorder (CVID)." (PMID 41246352, 2025).
coronary atherosclerosis (2 papers, 2022 to 2026). Atherosclerosis of the coronary vasculature. "Human IRF2BP2 genetic polymorphisms that reduce IRF2BP2 expression are tied to coronary atherosclerosis and coronary artery calcification." (PMID 35865523, 2022).
COVID-19 (2 papers, 2021 to 2022). A disease caused by infection with severe acute respiratory syndrome coronavirus 2. "In particular, mutations in TNFRSF13B, UBA1, IRF2BP2, and FCN3 were already reported to be associated with severe COVID-19." (PMID 36552859, 2022). "Eight ISGs were downregulated in Asymptomatic as compared with severe COVID-19 cases; CNP, CSF1, IRF1, IFITM10, IRF2BP2, IRF2BPL, SLC25A28 and SOCS3." (PMID 34824360, 2021). "Of these, nine ISGs were differentially regulated in Asymptomatic versus mild COVID-19 cases; IFNAR2, IRF2BP1, IRF4, MAVS, and TRIM14 were upregulated; whilst IRF2BP2, IRF2BPL, and SOCS3 were downregulated." (PMID 34824360, 2021). "Comparison of severe and mild Symptomatic COVID-19 cases revealed an upregulation of CD177, the neutrophil marker, CXCL16, MAPKMAPK2 and IRF2BP2 with downregulation of ISGs; IFIT, IFIT3, OAS1, OAS2, LY6E and MX1 in severe cases." (PMID 34824360, 2021).
gastric cancer (2 papers, 2019 to 2020). A primary or metastatic malignant neoplasm involving the stomach. "IRF2BP2 as a transcriptional repressor overexpresses in gastric cancer cells, which is closely related to proliferation, migration, and invasion in gastric cancer." (PMID 32566649, 2020). "However, the clinical significance and roles of IRF2BP2 in human gastric cancer (GC) remain uncertain." (PMID 31559693, 2019).
hepatocellular carcinoma (2 papers, 2021 to 2024). A malignant tumor that arises from hepatocytes. "Interestingly, IRF2BP2 overexpression in two hepatocellular carcinoma (HCC) cell lines (HepG2 and Huh7 cells) negatively regulated YAP activity and decreased the expression levels of YAP target genes." (PMID 33996817, 2021). "Given that IRF2BP2 exhibits potent tumor-suppressor activity in the hepatocellular carcinoma (HCC), we explored whether IRF2BP2 is an authentic SPOP substrate primarily in liver cancer cells." (PMID 38409107, 2024).
ischemic stroke (2 papers, 2025). A stroke disorder caused by obstruction of blood flow to the brain, due to thrombotic (local blood clot formation) or embolic (due to a blood clot or other material traveling from another site) event. "In comparison, the interferon regulatory factor 2 binding protein 2 (IRF2BP2) is a transcriptional corepressor which acts as a protective factor in oxidative stress and inflammation in ischemic stroke." (PMID 40362186, 2025). "The identification of super-enhancer-driven genes, specifically “ARAP3,” and “IRF2BP2,” as potential targets in ischemic stroke aligns with previous studies that highlighted the role of these genes in neuroinflammatory processes and cellular responses to ischemic injury." (PMID 40109665, 2025).
liver cancer (2 papers, 2024). An epithelial or non-epithelial malignant neoplasm that arises from the liver. "Recent studies have uncovered that IRF2BP2 cooperates with transcriptional suppressor VGLL4 to inhibit YAP-TEAD4 activity, thereby suppressing the progression of YAP-induced liver cancer." (PMID 38409107, 2024).
mesenchymal chondrosarcoma (2 papers, 2014). A morphologic variant of chondrosarcoma arising from bone and soft tissue. "Recently, a novel fusion between IRF2BP2 and the CDX1 homeobox gene was described in a patient suffering from a mesenchymal chondrosarcoma." (PMID 24970810, 2014).
myeloma (2 papers, 2021 to 2024). "Alterations in the IRF2BP2 gene were predicted to be a potential prognostic markers and therapeutic targets in the treatment and management of multiple myeloma." (PMID 33996817, 2021). "Although the expression of IRF2BP2 at the mRNA level was not investigated, chromosome 1q gain is frequently associated with poor prognosis for myeloma patients." (PMID 33996817, 2021). "Additionally, 23% of the mutations in our study (p = 3.1 × 10−10; OR = 3.8) were found in genes that are recurrently mutated in human myeloma (defined as a mutation present in at least 2 patients) including the BCL6 interacting factor Dnah9 and the immunomodulating factor Irf2bp2." (PMID 39198400, 2024). "Nonetheless, the mechanisms involved in lining IRF2BP2 expression to the malignancy of plasma cells during the evolution from MGUS to multiple myeloma (MM) were not explored." (PMID 33996817, 2021).
myoepithelial tumor (2 papers, 2025). A benign or malignant tumor characterized by the presence of cells that show myoepithelial differentiation. "Given its rarity, the prognostic significance of the IRF2BP2::CDX1 gene fusion in myoepithelial tumors of soft tissue is uncertain, with surgical excision being the mainstay of treatment in morphologically low-grade tumors at this point in time." (PMID 40978976, 2025). "Our case technically would be the third myoepithelial tumor of soft tissue to harbor an IRF2BP2 gene fusion and the first fully characterized case with a novel CDX1 gene fusion partner and rare morphologic features." (PMID 40978976, 2025). "It is uncertain at this point in time if the presence of an IRF2BP2 and CDX1 gene fusion contributes to or affects the vascular milieu of myoepithelial tumors of soft tissue." (PMID 40978976, 2025).
psoriasis (2 papers, 2025). An autoimmune condition characterized by red, well-delineated plaques with silvery scales that are usually on the extensor surfaces and scalp. "Individual roles of IRF2BP2, as well as its interaction with IRF2 in the IRF2/IRF2BP2 repression complex, have been described in autoimmune diseases, including asthma, multiple sclerosis, atopic dermatitis, and psoriasis, where CHROMR has been implicated." (PMID 40559622, 2025). "An in vitro model of psoriasis demonstrated that miR-155-5p acts as a proinflammatory factor by exacerbating inflammatory response via the IRF2BP2/KLF2/NF-κB pathway." (PMID 39934489, 2025).
Sepsis (2 papers, 2021 to 2022). Sepsis is defined as life-threatening organ dysfunction caused by a dysregulated host response to infection. "During sepsis, lipopolysaccharide (LPS) activates the pro-inflammatory effects of the miR-155-5p/IRF2BP2/NFAT1 axis, leading to loss of lung or heart function." (PMID 36389695, 2022). "Animal models of sepsis have shown that cardiac overexpression of IRF2BP2 effectively inhibits sepsis-induced cardiac dysfunction, inflammatory response, and cell death through activation of the AMPK signaling pathway." (PMID 36389695, 2022). "A similar LPS-induced elevation in IRF2BP2 in the heart of mice has been reported in a study of sepsis-induced cardiomyopathy." (PMID 34760935, 2021).
acute lymphoblastic leukemia (1 paper, 2024). Leukemia with an acute onset, characterized by the presence of lymphoblasts in the bone marrow and the peripheral blood. "IRF2BP2 is crucial for the growth and survival of T‐cell acute lymphoblastic leukemia (T‐ALL) cells." (PMID 39454110, 2024).